GPR55 (G protein-coupled receptor 55)
Diseases named in the same sentence as GPR55 in open-access papers (continued):
Sharing a sentence is not in itself a finding about the gene and the disease.
GPR55 also shares sentences with these, for which no sentence is quoted: multiple sclerosis (4 papers); brain tumors (2); Glucose intolerance (2); Impaired glucose tolerance (2); inflammatory bowel disease (2); Parkinson (2); acute myocardial infarction (1); amyotrophic lateral sclerosis (1); asthma (1); astrocytoma (1); Borderline personality disorder (1); Bradycardia (1); breast tumors (1); Chronic colitis (1); contact dermatitis (1); Crohn disease (1); endometrial carcinoma (1); Endometrioid Carcinoma (1); frontotemporal dementia (1); gastric cancer (1); gastrointestinal disorders (1); Hyperglycemia (1); Hyperinsulinemia (1); hypertriglyceridemia (1); Infertility (1); kidney injuries (1); melasma (1); memory impairment (1); metabolic syndrome (1); neuropathic pain (1).
A further 11 diseases each share a sentence with GPR55 in 1 paper.